YAP1 (Yes1 associated transcriptional regulator)
Diseases named in the same sentence as YAP1 in open-access papers (continued):
Sharing a sentence is not in itself a finding about the gene and the disease.
Myotonia (1 paper, 2025). An involuntary and painless delay in the relaxation of skeletal muscle following contraction or electrical stimulation. "In Mbnl1−/− mice without myotonia, uniquely mis-spliced genes are predominantly associated with cytoskeleton organization and the Yap-Tead complex, comprising the transcription factor YAP1 and its coactivator TEAD1, both of which respond to mechanical stimuli (right dot plot)." (PMID 41000779, 2025). "Notably, exon skipping events in Yap1 and Tead1 were detected exclusively in mice without myotonia, absent in those with myotonia." (PMID 41000779, 2025).
neutropenia (1 paper, 2025). A decrease in the number of neutrophils found in the blood. "Genetic ablation of TEAD1a or disruption of its interaction with Yes‐associated protein 1 (YAP1) induces profound neutropenia." (PMID 40874937, 2025).
ocular surface squamous neoplasia (1 paper, 2023). "Yet, the activity of YAP-1 in ocular surface squamous neoplasia (OSSN) has not been determined." (PMID 37476371, 2023).
oropharyngeal cancers (1 paper, 2022). Carcinoma, predominantly squamous cell, arising from the epithelial cells of the oropharynx. "HPV-positive oropharyngeal cancers harbor few mutations in the Hippo signaling pathway compared to HPV-negative cancers at the same anatomical site, prompting the hypothesis that an HPV-encoded protein inactivates the Hippo pathway and activates the Hippo effector yes-associated protein (YAP1)." (PMID 35170430, 2022).
osteoblastic osteosarcoma (1 paper, 2018). A conventional osteosarcoma characterized by the predominance of osteoid matrix. "Moreover, the lncRNA H19 is abnormally expressed by the Hh/Gli signalling pathway and Yap1 overexpression, suggesting that the Hh pathway is an important regulator of osteoblasts during the tumourigenesis of osteoblastic osteosarcoma via the overexpression of Yap-1 and the lncRNA H1969." (PMID 29899399, 2018).
ovarian clear cell cancer (1 paper, 2025). An invasive malignant neoplasm that arises from the ovary and is characterized by a predominance of clear and hobnail malignant epithelial cells. "It has been reported that ZDHHC7 may regulate the nuclear localization of YAP1 in ovarian clear cell carcinoma, and the inhibition of ZDHHC7 enhances ferroptosis by activating YAP1, although it is uncertain whether YAP1 is palmitoylated." (PMID 40814339, 2025).
Ovarian cyst (1 paper, 2019). The presence of one or more cysts of the ovary. "Deletion of Lats1 results in germ cell loss and formation of ovarian cysts and stromal tumors, while ovarian fragmentation leads to YAP1 upregulation and increased follicular development." (PMID 31883523, 2019).
pancreatic neuroendocrine cancers (1 paper, 2023). "Similar findings have been reported in a mesenchymal subgroup of pancreatic neuroendocrine cancers with elevated YAP1 activity." (PMID 37370765, 2023).
parathyroid carcinomas (1 paper, 2021). "Therefore, we are tempted to speculate that the loss of parafibromin in parathyroid cancer cells contributes to the reduction in YAP1 nuclear accumulation and transcriptional function." (PMID 33670622, 2021). "By contrast, in parathyroid cancers, YAP1 was variably downregulated in the cytoplasm and at the nuclear level." (PMID 33670622, 2021). "By contrast, parathyroid carcinomas (PCas) showed a remarkable loss of YAP1 nuclear staining irrespective of the cell division cycle 73 (CDC73) or MEN1 status." (PMID 33670622, 2021). "In particular, parathyroid cancers harboring CDC73 inactivating mutations, a frequent genetic aberration occurring in about 70% of parathyroid cancers, showed a reduced proportion of YAP1 nuclear positive cells, while they were lost in samples harboring the CDC73 wild type allele." (PMID 33670622, 2021).
Pca (1 paper, 2023). "In PCa, YAP1 has been identified as a binding partner of AR and co-localized with AR in an androgen-dependent manner and in an AI manner in CRPC." (PMID 36979713, 2023). "Our bioinformatics analysis suggested a link between NEK1 and YAP1 in different cancers; the YAP1 protein is also abundant in high grade PCa tumors despite the progressive downregulation of YAP1 mRNA expression." (PMID 36979713, 2023). "As YAP1 serves as the co-activator of AR in PCa model, we generated a NEK1KO (NEK1+/−) -TRAMP genetic mouse model." (PMID 36979713, 2023). "We further present evidence that targeting the activity of TLK1 as a druggable upstream activator of the NEK1>YAP1>CRPC pathway can be an important step in the management of PCa along with standard anti-androgen therapy in combination with a powerful inhibitor of TLK1 such as J54 (rev." (PMID 36979713, 2023). "We now provide evidence that the NEK1>YAP1 activation pathway is critical for PCa development and CRPC progression in the TRAMP model and in LNCaP cells, confirming previous work which showed that YAP1 overexpression in LNCaP cells rapidly converts them to androgen-independent (AI) growth." (PMID 36979713, 2023). "Therefore, it is conceivable that treatment of a sub-population of CRPC patients wherein their PCa cells rely partly on YAP1 upregulation and/or Y407 phosphorylation may benefit from a concomitant antiandrogen and J54 combination." (PMID 36979713, 2023). "Transcriptional co-activator YAP1, which acts downstream of the canonical Hippo kinases, is known to interact with a plethora of proteins, including TMPRSS2-ERG and the AR in PCa (rev." (PMID 36979713, 2023). "However, the activators of the Hippo/YAP1 in PCa remain unclear." (PMID 36979713, 2023). "In order to confirm the generality of the Y407F instability and the importance of NEK1-mediated YAP1 phosphorylation, we stably transfected LNCaP PCa cells with GFP-YAP1-WT and GFP-YAP1-Y407F and examined YAP1 expression." (PMID 36979713, 2023). "In fact, we observed that staining intensity for YAP1 was not much different for GS3 PCa than it was for “normal” hyperplastic glands sections." (PMID 36979713, 2023). "We previously reported that androgen deprivation therapy (ADT) or anti-androgens results in the activation of the TLK1B>NEK1>YAP1 pathway and induction of EMT and stemness genes, which we proposed to be critical for mCRPC progression and correlated with bioinformatics analyses of PCa data in TCGA." (PMID 36979713, 2023).
pleomorphic liposarcoma (1 paper, 2019). Pleomorphic liposarcoma (PLS), the rarest subtype of liposarcoma (LS), is an aggressive, fast growing tumor located usually in the deep soft tissues of the lower and upper extremities. "Intratumoral concordance of nuclear YAP1 and TAZ positivity was demonstrated in more than 28% of all SySa, pleomorphic liposarcoma (PLS), MPNST and MLS tissue specimens, though a considerable number of tumors appeared to express only one of the two oncoproteins." (PMID 31873172, 2019).
Pleural effusion (1 paper, 2017). The presence of an excessive amount of fluid in the pleural cavity. "Taking these observations into consideration, we speculated that HA in pleural effusion may promote progression of MPMs by stimulating the YAP1/TAZ-RHAMM axis." (PMID 29212185, 2017).
Premature ovarian insufficiency (1 paper, 2023). Amenorrhea due to loss of ovarian function before the age of 40. "In reproductive diseases affecting follicle development such as premature ovarian insufficiency (POI), Yes-associated protein (YAP, also known as YAP1), a key effector of the Hippo pathway, has been reported as a susceptibility gene of it." (PMID 37223010, 2023).
Primary Ovarian Insufficiency (1 paper, 2025). "Consistent with this, dysregulation of β-catenin and Hippo/Yap1 has been shown in conditions of disrupted follicle growth including PCOS, as well as Primary Ovarian Insufficiency (POI) and fibrosis." (PMID 40728874, 2025).
psoriasis (1 paper, 2025). An autoimmune condition characterized by red, well-delineated plaques with silvery scales that are usually on the extensor surfaces and scalp. "In the present study, we first validated the up-regulation of YAP1 in psoriasis lesions using psoriatic and healthy skin collected from our department." (PMID 40108109, 2025). "Our mechanistic study showed that YAP1 contributes to psoriasis pathogenesis by promoting the proliferation and inflammation of keratinocytes." (PMID 40108109, 2025). "By a sideways approach, we showed that inhibition of YAP1 by VP impedes the activation of keratinocytes, demonstrating the essential role of YAP1 in psoriasis development." (PMID 40108109, 2025). "The mRNA expression of psoriasis-related genes, as well as Yap1 gene, was obviously elevated in the IMQ-treated mouse epidermis (marked in a red box)." (PMID 40108109, 2025). "In the present study, we confirmed the up-regulation of YAP1 in psoriasis keratinocytes by measuring its expression in psoriatic patient skins, psoriatic-like cellular model, and IMQ-induced mouse model." (PMID 40108109, 2025). "In conclusion, our results demonstrate that YAP1 acts as a positive regulator of psoriasis pathogenesis by promoting the proliferation and inflammation of keratinocytes." (PMID 40108109, 2025). "The therapeutic potential of the YAP1 antagonist (VP) was then assessed on the psoriasis mouse model." (PMID 40108109, 2025). "Meanwhile, stimuli, such as psoriasis-related inflammatory factors, dramatically increase YAP1 expression." (PMID 40108109, 2025). "Meanwhile, the IHC analysis showed that YAP1 proteins were significantly up-regulated in psoriasis lesions than healthy controls." (PMID 40108109, 2025). "To confirm the effects of YAP1 in psoriasis development, we intradermally injected synthetic si-Yap1 into the shaved back of mice to knockdown Yap1 in vivo." (PMID 40108109, 2025). "In addition, si-Yap1 decreased psoriasis-related genes in the mouse skins topically administrated with IMQ." (PMID 40108109, 2025). "To figure out whether YAP1 is dysregulated by psoriasis-related inflammatory factors in vitro, we treated HaCaT cells with M5 to induce psoriatic-like inflammation in cultured keratinocytes." (PMID 40108109, 2025). "Importantly, knockdown/pharmacological blocking of Yap1 inhibited the immunopathological changes and prevented the psoriasis development in the IMQ-induced mouse model." (PMID 40108109, 2025). "However, further pre-clinical or clinical studies are required to confirm the therapeutic value of targeting YAP1 in psoriasis patients." (PMID 40108109, 2025). "YAP1 mRNA was dramatically increased in the psoriasis lesions collected by our dermatologists." (PMID 40108109, 2025). "Moreover, intradermal injection of si-Yap1 or VP hindered psoriasis development by impeding epidermal hyperplasia and relieving systemic inflammatory response in the IMQ-induced mouse model." (PMID 40108109, 2025). "Thus, Yap1 knockdown inhibits the immunopathological changes and blocks psoriasis development in vivo." (PMID 40108109, 2025). "Additionally, si-Yap1 significantly decreased the expression of psoriasis-related genes, including S100a7, S100a8, and S100a9." (PMID 40108109, 2025). "Importantly, functional or pharmacological inhibition of YAP1 prevents psoriatic development in vitro and in vivo, suggesting the potential of therapeutic approaches targeting YAP1 in psoriasis treatment." (PMID 40108109, 2025). "Interestingly, YAP1 knockdown led to decreased keratinocyte proliferation, suggesting its contributory role to epidermal hyperplasia, which is one of the main characteristics for psoriasis." (PMID 40108109, 2025). "Therefore, YAP1 represents a novel therapeutic target for the treatment of psoriasis." (PMID 40108109, 2025).
psoriasis (continued). "Therefore, our findings suggest that YAP1 plays a crucial role in psoriasis pathogenesis through modulating keratinocyte activation and may serve as a novel target for the treatment of psoriasis." (PMID 40108109, 2025). "To further explore the possible role of YAP1 in psoriasis pathogenesis, we examined its expression in psoriasis lesional and non-lesional skins." (PMID 40108109, 2025). "By analyzing the GEO database, we found that YAP1 was significantly elevated in the psoriasis lesional skins, compared to the non-lesional skins." (PMID 40108109, 2025). "Interestingly, the psoriasis-related inflammatory factors, including TNF-α, IL-17, IL-22, OSM, and IL-1α, promoted YAP1 up-regulation in keratinocytes, as indicated by increased YAP1 expression (& f)." (PMID 40108109, 2025). "However, the function of YAP1 in psoriasis has not been systematically studied." (PMID 40108109, 2025).
radiation dermatitis (1 paper, 2022). "• YAP1 overexpression in skin specimens of radiation dermatitis from FICRD patient." (PMID 34689211, 2022).
rectal adenoma (1 paper, 2017). "First, in Sabates-Bellver colon database, composing of 64 clinical samples from different regions, YAP1 messenger RNA (mRNA) was significantly elevated in both colon and rectal adenoma samples." (PMID 28241877, 2017).
Right ventricular hypertrophy (1 paper, 2023). In this case the right ventricle is more muscular than normal, causing a characteristic boot-shaped (coeur-en-sabot) appearance as seen on anterior- posterior chest x-rays. "The preventative/reversal knockdown of USP15 in vivo evidently inhibited pulmonary vascular wall thickening, right ventricular hypertrophy, and YAP1/TAZ signaling in animals with experimental PH." (PMID 36635430, 2023).
serous carcinoma (1 paper, 2024). "We have shown that hyperactivation of YAP1 in immortalized fallopian tube epithelial cells induced high-grade serous carcinoma." (PMID 39271776, 2024). "The interaction between YAP1 and HPV greatly promoted the progression and metastasis of fallopian tube-derived high grade serous carcinoma." (PMID 39271776, 2024).
Skin ulcer (1 paper, 2020). A discontinuity of the skin exhibiting complete loss of the epidermis and often portions of the dermis and even subcutaneous fat. "After 10–20 days of induction, mice showed changes in hair color, hair loss, skin ulcer formation, and general discomfort, indicating disruption of skin homeostasis by YAP1/TAZ-TEAD blockage." (PMID 32193376, 2020).
spinal cord injury (1 paper, 2026). Penetrating and non-penetrating injuries to the spinal cord resulting from traumatic external forces (e.g., WOUNDS, GUNSHOT; WHIPLASH INJURIES; etc.). "Following spinal cord injury (SCI), the transcriptional regulator yes-associated protein 1 (YAP1) is upregulated and accumulates in the nuclei of astrocytes, where it promotes reactive astrogliosis—a process that critically influences wound healing and neurological function recovery." (PMID 41522361, 2026).
staphylococcus aureus infection (1 paper, 2023). An infectious process in which the bacteria Staphylococcus aureus is present. "In YAP1‐mutated phagocytic cells, the autophagic process was suppressed because of decreased YAP1‐TEAD transcriptional activity during Staphylococcus aureus infection." (PMID 37665055, 2023).
tendinopathy (1 paper, 2025). "Our findings demonstrated that FHL2 supplementation after tendon injury can noticeably decrease YAP1/sFRP2 expression, inhibit vascular remodeling associated with tendinopathy and restore tissue structure despite some differences from normal tendon tissue." (PMID 41258071, 2025). "By contrast, downregulation of FHL2 expression and upregulation of YAP1/sFRP2 expression are strongly and positively correlated with the temporal pathological remodeling and angiogenesis associated with tendinopathy." (PMID 41258071, 2025). "This study revealed that low FHL2 expression-induced upregulation of YAP1/sFRP2 may be a critical mechanism underlying vascular remodeling in tendinopathy." (PMID 41258071, 2025). "sFRP2 expression in tendinopathy is associated with the Hippo/YAP1 signaling pathway." (PMID 41258071, 2025). "This study reveals that FHL2/YAP1/sFRP2-mediated vascular remodeling drives tendinopathy progression." (PMID 41258071, 2025). "This study employed exercise-induced (treadmill) and trauma-induced rat tendinopathy models to investigate the FHL2/YAP1/sFRP2 axis in the context of angiogenesis." (PMID 41258071, 2025). "In conclusion, this study systematically explored the progression of tendinopathy and its pathological relationship with vascular instability, highlighting the critical role of vascular remodeling via the FHL2/YAP1/sFRP2 signaling axis." (PMID 41258071, 2025). "Although Col-III expression decreased in the Inj/YAP1KD group, Col-I levels were downregulated (versus Ctl/NC group, P < 0.05), suggesting that YAP1 knockdown may not be an optimal strategy for treating pathological remodeling in tendinopathy." (PMID 41258071, 2025). "Thus, in tendinopathy, FHL2 overexpression may primarily suppress inflammatory angiogenesis via its anti-inflammatory effects, thereby improving perfusion and promoting repair, potentially mediated by the YAP1/sFRP2 axis." (PMID 41258071, 2025). "However, we found that YAP1 knockdown increases apoptosis, suggesting that YAP1, as a key regulator of several growth and developmental signaling pathways, may not be an optimal therapeutic target for treating tendinopathy." (PMID 41258071, 2025).
thymic epithelial tumours (1 paper, 2026). "The MAML2 gene fusions (KMT2A::MAML2, YAP1::MAML2, and CRTC1::MAML2), which have been observed in a small subset of thymic epithelial tumours, were not identified in our cohort." (PMID 41344988, 2026).
ulcerative colitis (1 paper, 2022). An inflammatory bowel disease involving the mucosal surface of the large intestine and rectum. "Nuclear YAP1 drove intestinal epithelial cell proliferation, which could cause post-inflammatory epithelial regeneration in ulcerative colitis." (PMID 35979359, 2022).
urothelial carcinoma in the (1 paper, 2022). "YAP1 expression has also been proposed as a prognostic indicator in patients with urothelial carcinoma in the bladder." (PMID 35358000, 2022).
van Maldergem syndrome (1 paper, 2020). "Whether the role of 14-3-3ε in the regulation of Yap1 and Hippo signaling also contributes to Van Maldergem syndrome is not clear." (PMID 32170161, 2020).
viral pneumonia (1 paper, 2025). Inflammation of the lung parenchyma that is caused by a viral infection. "In addition, lung viral infections elicit a robust IFN-gamma response, which activates the focal adhesion kinase/YAP1 pathway to promote dysplastic cell formation, an essential step in alveolar remodeling in patients with severe viral pneumonia." (PMID 40784457, 2025).